STAT3 (signal transducer and activator of transcription 3)
Diseases named in the same sentence as STAT3 in open-access papers (continued):
Sharing a sentence is not in itself a finding about the gene and the disease.
cancer (continued). "Consistent with this, blocking STAT3 activity with antioxidants, as well as STAT3 activation by reactive oxygen species has been shown to enhance cell survival, while mitochondrial overexpression of STAT3 promoted the growth of cancer cells." (PMID 25268165, 2014). "Based on these results, we hypothesized that activation and over-expression of STAT3 induces anoikis resistance in cancer cells and promotes metastasis." (PMID 25216522, 2014). "Thus, STAT3 can directly up regulate multiple transcription factors that can reprogram cells to induce and sustain pluripotency supporting a cancer stem cell phenotype." (PMID 24743777, 2014). "In this context, STAT3 inhibition might be an effective approach in the treatment of cancers in which STAT3 is aberrantly activated." (PMID 25359779, 2014). "ERα was bound to both HER2 and STAT3 simultaneously in MCF7-HER2 cancer cells." (PMID 24297508, 2014). "A key cancer-promoting downstream effect of innate immune signaling could be the induction of cell proliferation and survival pathways mediated by NF-κB and STAT3 (signal transducer and activator of transcription 3)." (PMID 25256712, 2014). "The experimental results summarized in this review have highlighted the concept that STAT3 can be friend or foe in cancer, and there are a relatively large number of factors that are known to dictate how STAT3 affects the malignant phenotypes and clinical behaviors of cancer." (PMID 24995504, 2014). "VEGF expression has been found to correlate with STAT3 activity in diverse human cancer cell lines." (PMID 24520293, 2014). "Phosphorylated STAT3 levels were initially decreased but strongly increased after sustained treatment with dasatinib, suggesting the existence of a compensatory feedback pathway that supports cancer cell survival by regulating STAT3 activity." (PMID 24662938, 2014). "Indeed, Western blot analysis showed that in addition to STAT3, the phosphorylation (activity) of other proteins playing key signaling roles in cancer cells, AKT and ERK1/2, were suppressed after the treatment with glucosamine in DU145 cells." (PMID 24932134, 2014). "One of the possible KNPA4 target is STAT3 protein, whose aberrant activation and translocation into the nucleus promotes initiation and progression of human cancers by either inhibiting apoptosis or inducing cell proliferation, angiogenesis, invasion, and metastasis." (PMID 24866763, 2014). "Hence, knocking out STAT3 not only decreased anoikis resistance but also inhibited the migratory potential of anoikis resistant cancer cells." (PMID 25216522, 2014). "Signal transducer and activator of transcription 3 (Stat3) transduces signals of many peptide hormones from the cell surface to the nucleus and functions as an oncoprotein in many types of cancers, yet little is known about how it achieves its native folded state within the cell." (PMID 24756126, 2014). "STAT3 is frequently constitutively activated in many human cancers." (PMID 24743777, 2014). "STAT3 has been hypothesized as a potential target to modulate paclitaxel sensitivity in cancer patients." (PMID 24699359, 2014). "Moreover, this cancer-promoting activity was due at least in part to the IL-6/STAT-3 signaling pathway." (PMID 25419563, 2014). "The suppression of constitutively active STAT3 in HCC cells raises the possibility that garcinol might also suppress constitutively activated STAT3 in other types of cancer cells." (PMID 24655440, 2014). "Therefore, the question arises on the role of Src, an oncogene often activated in cancer, and its effector Stat3 upon GJIC." (PMID 24670366, 2014). "Consequently, STAT3 has emerged as a promising target for cancer therapy, which is pharmacologically safe and effective, and blocking STAT3 activation has the potential for treatment of HCC." (PMID 24418169, 2014).
cancer (continued). "Mounting evidence has shown that constitutive activation of STAT3 is a frequent biochemical aberrancy in cancer cells, and this abnormality directly contributes to tumorigenesis and shapes many malignant phenotypes in cancer cells." (PMID 24995504, 2014). "A more appropriate assay may be one using OSM and/or a combination of cytokines as the inducer, but the choice should optimally be driven by an understanding of the pathway and the role heterogeneity plays in the dysregulation of STAT3 in cancer tissue." (PMID 25036749, 2014). "Thus, the suppression of STAT3 signaling pathway has emerged as an effective way for cancer therapy." (PMID 25180593, 2014). "In conclusion, pSTAT3 Tyr705 is highly expressed by HOCCs as well as in areas of necrosis and presumed our findings provide additional evidence of S1PR1's involvement in STAT3 activation and, for the first time, demonstrate this effect in hypoxic cancer cells and tumors." (PMID 25594014, 2014). "Interestingly, STAT3 activation of miR-21 via PTEN has been described as a part of an epigenetic switch that links inflammation to cancer." (PMID 25539644, 2014). "STAT3 is overactive in a variety of cancers, so STAT3 inhibition may be a viable approach for cancer therapeutics." (PMID 24589581, 2014). "It was reported that several signaling pathways, like phosphorylation of Akt or STAT3, may contribute to the cancer cells growth and progression." (PMID 25221777, 2014). "The aim of this study was to determine whether garcinol exerts its anti-cancer effects in HCC cells through the abrogation of the STAT3 signaling pathway, targeting the post-translational modification of STAT3 and dimerization of the transcription factor." (PMID 24655440, 2014). "List of different drugs targeting STAT3 signaling pathway in cancers." (PMID 24722453, 2014). "To test our hypothesis that STAT3 plays a role in anoikis resistance, we wanted to determine whether STAT3 inhibitors can overcome aniokis resistance in cancer cells." (PMID 25216522, 2014). "STAT3 is necessary for tumorsphere formation in HER2-overexpressing cancer." (PMID 24297508, 2014). "In addition, when we knocked down the STAT3 gene, CD44+ subpopulation was reduced, suggesting the pivotal role of STAT3 in the cancer stem cell transition in HER2 amplified environment." (PMID 24297508, 2014). "The IL-6/STAT3 pathway plays an important role in human cancers." (PMID 25344679, 2014). "Finally, it should be noted that S727 STAT3 phosphorylation is needed for constitutive activation of STAT3 and cell invasion in various human cancers." (PMID 24410832, 2014). "These conclusions are consistent with previous reports that striking coincidences for concerted aberrant activation of both STAT3 and c-Jun in human cancer specimens are observed, and c-Jun or c-Myc is required for the transforming activity of STAT3 in tumorgenesis." (PMID 25070240, 2014). "Therefore, F-actin and STAT3 have been generally considered as their potential molecular targets in cancer cells." (PMID 24505404, 2014). "The STAT3-VEGF circuit involves more than cancer cells within tumors." (PMID 24995504, 2014). "IL-6 is often upregulated in epithelial cancers, such as breast and prostate and the IL-6/STAT3 axis is often considered as part of a positive regulatory circuit operating in inflammatory setting to nourish cancer cells and allow to maintain their transformed phenotypes." (PMID 25026286, 2014). "As the degree of cancer invasiveness increases, the STAT3 phosphorylation cascade is altered." (PMID 24799285, 2014). "Recent evidence suggests that S1PR1 induces STAT3 activity in cancer cells." (PMID 25594014, 2014). "Furthermore, Mo-MDSC infiltrate tumors where they promote cancer stemness in a STAT3-dependent manner." (PMID 24652403, 2014). "We further investigated the influence of STAT3 on IDO expression in cancer cells." (PMID 24657910, 2014). "Development of STAT3 inhibitors is currently demanded for either cancer prevention or treatment." (PMID 24743778, 2014).
cancer (continued). "The use of such inhibitors may prevent STAT3-mediated senescence and allow the outgrowth of dormant or occult tumors, thereby promoting cancer progression." (PMID 24675570, 2014). "In addition, STAT3 is a common molecular target for blocking angiogenesis induced by multiple signaling pathways in various types of human cancer." (PMID 24520293, 2014). "Inhibiting STAT3 expression or phosphorylation using antisense oligonucleotides and small-molecule inhibitors suppressed the growth of human and murine tumors in animal models, demonstrating that STAT3 is a potential target for cancer therapy." (PMID 24662938, 2014). "Therefore, inhibition of STAT3 provides a rational strategy to block carcinogenesis at early stage of cancer development." (PMID 24743778, 2014). "Another study suggested that morin showed anti-cancer effects by STAT3 activity." (PMID 25561222, 2014). "As Stat3 signaling is up-regulated in many pathological conditions, including cancer and inflammatory diseases, insight into what controls its folding may be useful for the identification of vulnerabilities that can be therapeutically exploited." (PMID 24756126, 2014). "In addition, STAT3 also serves as a potential target for anticancer treatment and cancer prevention." (PMID 24945311, 2014). "In addition to E2/ERα, it has been documented that Akt and STAT3 are important cancer survival pathways in those cancer cells." (PMID 25221777, 2014). "Based on these studies, STAT3 is a pivotal regulator of cancer cell proliferation and apoptosis." (PMID 24743778, 2014). "Besides, the tumorigenic effects of IL-17 involve induction of IL-6 production, which in turn activates oncogenic signal transducer and activator of Stat3, which plays essential roles in the pathogenesis of many cancers." (PMID 25489847, 2014). "Also, H2O2 stimulates the activity of the STAT kinases JAK2 and TYK2 and activates STAT1 and STAT3 in fibroblasts, lymphocytes, and cancer cells." (PMID 24662938, 2014). "Our results provide the possibility that blocking the dimerization process or targeting on STAT3 may have therapeutic implication on GnT-V high-expressing cancer." (PMID 24846175, 2014). "Taken together, STAT3 is required and essential in tumorigenesis of a variety of cancers." (PMID 24743778, 2014). "Of the seven STATs, STAT3 is by far the most prominent in cancer." (PMID 25153725, 2014). "Thus, the status of these feedback loops not only within pathways, but also between pathways, can have a major effect on the biology of a cancer with activated STAT3." (PMID 24762632, 2014). "While similar effects have not yet been found in other cancer types, these findings suggest that it is important to understand the status of STAT5 (and perhaps other modifying transcription factors) before one can understand the functional effects of activated STAT3 in a cancer cell." (PMID 24762632, 2014). "Here, we hypothesized that the AHR and STAT3 are involved in driving IDO expression in human cancers." (PMID 24657910, 2014). "However, most STAT3 inhibitors have yet to be translated to clinical trials for cancer treatment, presumably because of pharmacokinetic, efficacy, and safety issues." (PMID 24662938, 2014). "If this result is validated in other diverse cancer cell types, we propose that STAT3 regulation may be important to cancer development and that it may also be an interesting target for the design of new drug strategies against cancer cells." (PMID 25417721, 2014). "To examine whether STAT3 inhibition might eliminate the ALDHhigh subpopulation, we treated cancer cells with different doses of Stattic." (PMID 25261365, 2014). "The mechanisms of STAT3 activation in GBMs are similar to those found in other cancer cell lines." (PMID 24518612, 2014). "STAT3 is highly expressed in OVCA and has been shown to confer drug resistance and induce growth‐promoting effects and is implicated in the malignant transformation of cancer cells." (PMID 24799285, 2014).
cancer (continued). "Since its discovery, the STAT3 transcription factor has been extensively studied for its function as a transcriptional regulator and its role as a mediator of development, normal physiology, and pathology of many diseases, including cancers." (PMID 24743777, 2014). "In addition, constitutive activation of STAT3 has been reported in several primary cancers and in many oncogene-transformed cells, indicating a direct oncogenic role of STAT310." (PMID 25476455, 2014). "MiR-181a was upregulated in SW480/STAT3-siRNA samples, which might be attributed to different cancer tissues." (PMID 25126546, 2014). "In addition, understanding these subtleties of STAT3 signaling in cancer pathogenesis will allow the development of more rational molecular approaches to cancer therapy." (PMID 24762632, 2014). "STAT3 has been shown to be dysregulated in cancer stem cells." (PMID 24743777, 2014). "c-SRC has been reported to increase STAT3 activity in carcinoma cells including MC." (PMID 25266665, 2014). "Moreover, STAT3 has been shown to mediate epithelial-to-mesenchymal transition (EMT) in different carcinomas, either alone or in combination with other triggers." (PMID 25268165, 2014). "Aberrant Stat3 activation has been reported to exist in numerous human carcinomas." (PMID 24348829, 2014). "The IL-6/JAK/STAT pathway is a key signal transduction pathway implicated in the pathogenesis of many human cancers, suggesting that kinase inhibitors targeting JAK/STAT3 may have a broad spectrum of antitumor activity." (PMID 23531921, 2013). "Our findings suggest that Spica Prunellae may be a potential novel therapeutic agent for the treatment of cancers with constitutive activation of STAT3." (PMID 23800091, 2013). "The constitutive activation of STAT3 results in the development of various types of cancer." (PMID 24179517, 2013). "STAT3 is activated in multiple human cancers and was shown to function as an oncogene." (PMID 23940556, 2013). "Therefore, our study suggests that STAT3 is a novel molecular target for scoparone, and that scoparone represents an anti-cancer drug candidate for the treatment of cancers in which the STAT3 signaling pathway is constitutively active." (PMID 24260381, 2013). "Song and coworkers reported that cisplatin inhibits JAK2/STAT3 signaling in cancer cells." (PMID 24199193, 2013). "In addition to its role in numerous cellular functions, there is strong evidence correlating Stat3 activation and cancer." (PMID 23577258, 2013). "Persistent activation of STAT3 occurs with high frequency in human cancers." (PMID 24170218, 2013). "This could explain why constitutive activation of STAT3 is contributing to the cancer stem cell phenotype." (PMID 24386318, 2013). "Niclosamide has recently been reported as a potent STAT3 inhibitor against cancer cells." (PMID 24019973, 2013). "Therefore, STAT3 is now considered to represent a promising molecular target for development of anti-cancer therapeutics using both direct and indirect approaches." (PMID 24260381, 2013). "Spica Prunellae possesses a broad range of anti-cancer activities due to its ability to affect STAT3 pathway, suggesting that Spica Prunellae could be a novel potent therapeutic agent for the treatment of CRC." (PMID 23800091, 2013). "Currently, the oncogenic transcription factor STAT3 has attracted much attention as a pharmacologic target, although in vivo evidence demonstrating that inhibition of STAT3 could counteract cancer remains incomplete." (PMID 23663277, 2013). "Considering the facts that both STAT3 and Akt are critical kinases for the self-renewal and pluripotency of the cancer stem cells, it is plausible to combine gefitinib with agents that target STAT3 and Akt to prevent gefitinib resistance and the faster relapse of the tumors." (PMID 24280348, 2013). "STAT3 is over-expressed and/or post-translationally modified in the majority of human cancers." (PMID 24312439, 2013).
cancer (continued). "The higher level of p-STAT3 in cancer cells after the IL-6 treatment might account for a weaker response to enhanced STAT3 activation after EBV infection." (PMID 23658720, 2013). "STAT3 is constitutively activated in a wide variety of cancer types." (PMID 23382965, 2013). "Several studies have shown that STAT3 is a potential target for anti-cancer therapy." (PMID 24380387, 2013). "Therefore, the JAK/STAT3 or 5 signaling has been thought as a valuable molecular target for cancer therapy." (PMID 23878608, 2013). "Moreover, it was shown that when MDSCs were exposed to conditioned media of metastasizing cancer cells, MDSCs secreted exaggerated IL-6 and soluble IL-6Rα, which induced persistent activation of STAT3 in cancer cells." (PMID 24021059, 2013). "Although in many cancers STAT3 is not directly activated by oncogenic mutations, it exerts critical oncogenic functions in both cancer and immune cells within the microenvironment." (PMID 23987103, 2013). "Notably, IL-6 is a cytokine that can activate JAK2/STAT3 signaling in cancer cells, which has an important effect on oncogenesis." (PMID 23690956, 2013). "Presence of nuclear-localized STAT3 in human cancers implicates that STAT3 may serve as an oncogene to promote cancer development." (PMID 23940556, 2013). "While this review was submitted, a new study reported that glioma cancer stem cells exhibit high levels of nuclear activated STAT3 and NFkB, that interact and are bound to the promoter of the Notch gene, leading to induction of Notch and subsequently Notch-dependent gene expression in GCSCs." (PMID 23998913, 2013). "Thus, STAT3 activation inhibits doxorubicin-mediated p65 nuclear localization, which is contrary to data obtained in untreated cancer cells indicating that STAT3 promotes p65 nuclear retention." (PMID 23383209, 2013). "An IL-6 induced JAK/STAT3 signaling was essential for infiltration of circulating cancer cells." (PMID 23704931, 2013). "Therefore, direct or indirect inhibition of STAT3 activity has been suggested as a novel anti-cancer therapeutic strategy." (PMID 24260381, 2013). "Our results further strengthen the evidence that targeting p-STAT3 by enhanced SHP-1 activity may have anti-cancer potential." (PMID 23938089, 2013). "STAT3 is a transcription factor of central importance in chronic inflammation and cancer." (PMID 24192293, 2013). "Therefore, these cumulative observations have validated STAT3 as a novel target for cancer therapy, and hence provided the rationale for developing small-molecule STAT3 inhibitors." (PMID 24288468, 2013). "Consequently, constitutive activation of STAT3 is responsible for a variety of human cancers, including ovarian cancer, breast cancer, leukemia, prostate cancer, head and neck cancer, and pancreatic cancer." (PMID 24116074, 2013). "STAT3 is excessively active in many cancers and plays a central role in tumorigenesis." (PMID 24199193, 2013). "We speculated that berberine may be able to target cancer cells which are dependent on STAT3 activation for growth and survival." (PMID 24380387, 2013). "We hypothesize the interactions between CD44, STAT3 and hTERT signaling pathways that occur in the human malignancies are deregulated in the cancer stem cells." (PMID 24386318, 2013). "Excess Stat3 protein potentially contributes to the growth of cancers." (PMID 23401782, 2013). "Although STAT3 serves critical and necessary roles in early embryogenesis, its presence in the majority of normal adult cell types is largely dispensable, making it an attractive target for cancer therapy." (PMID 23382914, 2013). "STAT3 is also reported to have a leading role in cancer inflammation and immunity." (PMID 24324713, 2013).